TAB2 (TGF-beta activated kinase 1 (MAP3K7) binding protein 2)
Diseases named in the same sentence as TAB2 in open-access papers (continued):
Sharing a sentence is not in itself a finding about the gene and the disease.
heart failure (2 papers, 2022 to 2025). Inability of the heart to pump blood at an adequate rate to meet tissue metabolic requirements. "Mice with TAB2 deficiency were also predisposed to adverse cardiac remodeling and heart failure after pathological stimulation." (PMID 34990405, 2022). "Our data also demonstrated that aberrant RIPK1 kinase activation is a key effector driving myocardial apoptosis and necroptosis in vivo, which underlies cardiac remodeling and heart failure induced by TAB2 deficiency." (PMID 34990405, 2022). "Importantly, TAB2-deficient mice were predisposed to adverse cardiac remodeling and heart failure after pressure overload or MI, suggesting that TAB2 is also critical for the prevention of pathological cardiac remodeling and heart failure progression." (PMID 34990405, 2022). "Based on the data above from our Tab2-deficient mice, we hypothesize that Tab2 deficiency triggers adverse cardiac remodeling and heart failure by promoting apoptosis and/or necroptosis." (PMID 34990405, 2022). "From day 40 onwards, we observed a significant increase in the expression levels of ANP and BNP in TAB2 knockout cells, suggesting a progression towards heart failure." (PMID 39905300, 2025). "We further examined whether TAB2 plays a role in regulating myocardial remodeling and heart failure propensity after pathological stimulation." (PMID 34990405, 2022). "To evaluate the role of TAB2 in TAC- or MI-induced pathological remodeling and heart failure, here we used young Tab2fl/fl-αMHC-Cre mice (6 weeks of age), which displayed no detectable cardiac pathology at baseline." (PMID 34990405, 2022).
liver fibrosis (2 papers, 2023 to 2024). "This action on TAB2, which recognizes K63-linked ubiquitin chains of RIP1 in TNF-α signaling or TRAF6 in IL-1β signaling, consequently inhibits the TAK1-MAPK cascade, a pathway critical in liver fibrosis progression." (PMID 37867509, 2023). "Consequently, we posit that macrophage TAB2 may also be a pivotal gene influencing the progression of liver fibrosis." (PMID 39629085, 2024). "TRIM38 directly binds to TAB2, and recognizes the K63 of RIP1 in the TNF-α signaling pathway through TAB2 to connect the ubiquitin chain or TRAF6 in the IL-1β signaling pathway, thereby inhibiting the key pathway TAK1-MAPK cascade in the process of liver fibrosis." (PMID 37867509, 2023).
Stroke (2 papers, 2022). Sudden impairment of blood flow to a part of the brain due to occlusion or rupture of an artery to the brain. "Associated cardiovascular diseases include diabetes (PDLIM5, HDAC4, and TLE1), cardiac development (PDLIM5) and myocardial aging (CASP12), hypertension (PFKP and TAB2), and intracerebral and intraventricular bleeding (RUNX1) and stroke (AXIN2)." (PMID 36620623, 2022).
adenovirus infection (1 paper, 2023). "Since we proved that TRIM38 directly interacts with TAB2 and associates with its degradation, we overexpressed Tab2 via adenovirus infection in Trim38-overexpressed primary hepatocytes." (PMID 37116711, 2023). "To further testify whether the effects of TRIM38 in NAFLD depends on TAB2, we overexpressed Tab2 via adenovirus infection in Trim38 overexpressed primary hepatocytes." (PMID 37116711, 2023).
arteriosclerosis (1 paper, 2014). A vascular disorder characterized by thickening and hardening of the walls of the arteries. "TGF-β has been found to be an atheroprotective factor in arteriosclerosis, and the TGF-β/Smad pathway can suppress NF-kB activation-induced inflammation by blocking TAB2 or TAB3." (PMID 25198728, 2014).
asthma (1 paper, 2015). "The remaining 4 target genes were assessed based on previous literature: ATXN1 has been associated with asthma, NFAT5 is implicated in the regulation of proinflammatory cytokines, NR3C1 is a target for steroid-based asthma treatments and TAB2 is a validated miR-155-5p target." (PMID 26693910, 2015). "TAB2 is targeted by miR-23b and miR-155 and while no role for TAB2 has been identified in asthma, it is an adaptor in the TLR/IL-1 signaling cascade and may regulate inflammation in asthma." (PMID 26693910, 2015).
cervical squamous cell carcinoma (1 paper, 2021). A squamous cell carcinoma arising from the cervical epithelium. "It was found that the expression level of TAB2 was significantly positively correlated with that of BMI1 in cervical squamous cell carcinoma samples, which was also consistent with previous data." (PMID 34306095, 2021). "The StarBase database was used to analyze the coexpression of TAB2 and classical stemness molecules (BMI1 and SOX2) in 306 cervical squamous cell carcinoma samples." (PMID 34306095, 2021).
COVID-19 (1 paper, 2023). A disease caused by infection with severe acute respiratory syndrome coronavirus 2. "Hub genes identified from the protein–protein interaction (PPI) network, including DUSP6, BHLHE40, RASGRP1, and TAB2, are potential therapeutic targets in COVID-19 with AKI and CKD." (PMID 37026010, 2023). "DUSP6, BHLHE40, RASGRP1, and TAB2, the top 4 topological metric hub genes, appear to be pivotal molecular targets of COVID-19, AKI, and CKD." (PMID 37026010, 2023).
endometriosis (1 paper, 2024). The growth of functional endometrial tissue in anatomic sites outside the uterine body. "The PPI network analysis reveals hub genes, including BCL2, CCNA2, CDK7, EGF, GAS6, MAP3K7, and TAB2, which emerge as pivotal players in endometriosis progression." (PMID 39108650, 2024).
hypoplastic left heart syndrome (1 paper, 2021). Hypoplastic left heart syndrome (HLHS) refers to the abnormal development of the left-sided cardiac structures, resulting in obstruction to blood flow from the left ventricular outflow tract. "Cheng’s findings suggest that TAB2 haploinsufficiency is a risk factor for Hypoplastic left heart syndrome (HLHS) and expands the phenotypic spectrum of this microdeletion syndrome." (PMID 33974633, 2021).
ischemia (1 paper, 2025). A hypoperfusion of the BLOOD through an organ or tissue caused by a PATHOLOGIC CONSTRICTION or obstruction of its BLOOD VESSELS, or an absence of BLOOD CIRCULATION. "A recent report showed that TRIM27 plays a crucial role in regulating of hepatic ischemia/reperfusion injury by mediating the degradation of TAB2/3 and suppressing downstream TAK1–JNK/p38 signaling." (PMID 40251491, 2025).
ischemic stroke (1 paper, 2023). A stroke disorder caused by obstruction of blood flow to the brain, due to thrombotic (local blood clot formation) or embolic (due to a blood clot or other material traveling from another site) event. "AAV9‐mediated TAB2 knockdown ameliorates ischemic stroke injury and abolishes the effect of USP25 deletion." (PMID 37587766, 2023). "Noteworthy, TAB2 plays a key role in ischemic stroke injury." (PMID 37587766, 2023).
liver steatosis (1 paper, 2022). "Indeed, abnormal expression of TAB2 is associated with hepatic steatosis and inflammation in genetically obese mice." (PMID 39872354, 2022). "Adenovirus or adeno-associated virus-mediated overexpression of IGF2BP2 could induce liver steatosis, inflammation, and fibrosis in mice, at least in part, by increasing Tab2 mRNA stability." (PMID 39872354, 2022).
malignant epithelial ovarian tumors (1 paper, 2024). "TAB2 gene polymorphisms are known to be associated with malignant epithelial ovarian tumors." (PMID 39061149, 2024).
myocardial infarction (1 paper, 2022). Gross necrosis of the myocardium, as a result of interruption of the blood supply to the area, as in coronary thrombosis. "We first measured TAB2 protein expression in the heart subjected to transverse aortic constriction (TAC) or myocardial infarction (MI)." (PMID 34990405, 2022).
oral mucositis (1 paper, 2025). Inflammation of the mucous membranes of any of the structures in the mouth. "let-7e-5p was enriched in umbilical cord MSC extracellular vesicle and alleviated oral mucositis by targeting TAB2 and inhibiting NF-kB signaling." (PMID 40863041, 2025).
pituitary adenomas (1 paper, 2024). "This study investigated the relationship between specific gene polymorphisms (TRAF2, TAB2, IKBKB) and protein levels and pituitary adenomas (PAs)." (PMID 39061149, 2024).
primary cardiomyopathy (1 paper, 2022). "Patients with TAB2 deficiency often exhibit cardiac dysfunction arising from CHDs, while some display primary cardiomyopathy without CHDs." (PMID 34990405, 2022).
systemic lupus erythematosus (1 paper, 2024). An autoimmune multi-organ disease typically associated with vasculopathy and autoantibody production. "Over the last few decades, microRNA-155 (miR-155) has emerged as a key proinflammatory regulator in clinical and experimental arthritis and in systemic lupus erythematosus (SLE), targeting specific mRNAs, such as PU.1, SOCS-1, TAB-2, and c-Maf." (PMID 38542233, 2024).
viral infection (1 paper, 2021). "In the immune system, TAB2 plays a role on mediating in the IMD signaling pathway and takes on a great responsibility for the response to bacterial and viral infection." (PMID 33974633, 2021). "In the immune system, TAB2 works as an important intermediate in the IMD signaling pathway and take on a great responsibility for the innate response in response to bacterial and viral infection." (PMID 33974633, 2021).
tumor (20 papers, 2017 to 2025). "Increased expression of TAB2 has been shown to lead to the development of oral squamous cell carcinoma and promote tumor cell proliferation and is associated with a poor prognosis." (PMID 39061149, 2024). "To further elucidate the underlying mechanisms for the increased TAMs in TAb2 tumors, we established a co-culture system by employing bone-marrow (BM) cells that would contain myeloid precursors cultured in the absence or presence of TAb2 or TCh3 tumor cells." (PMID 35366939, 2022). "Hence, we conclude that TAb2 and TCh3 tumors harbor tumor-specific genetic differences that may underlie their differential phenotypes." (PMID 35366939, 2022). "The proliferation index was significantly higher in the group of BM plus TAb2 tumor cells than in BM alone." (PMID 39596341, 2024). "The presence of TAb2 tumor cells significantly promoted the expansion of M-MDSC compared with the BM-only control (BM vs. BM+TAb2)." (PMID 39596341, 2024). "The TAB2 protein is also known to promote the activation of EMT and PI3K-AKT signaling pathways associated with tumor cell metastasis and proliferation through indirect activation of NFκB." (PMID 39061149, 2024). "On the other hand, low expression of TAB2 suppresses the uncontrolled proliferation of tumor cells and promotes their apoptosis." (PMID 39061149, 2024). "We noticed that the presence of TAb2 tumor cells drastically expanded the Ly6C−Ly6G− population (BM vs. BM+TAb2), and most of this consisted of F4/80+ macrophages (BM+TAb2)." (PMID 39596341, 2024). "ICI unresponsive TAb2 tumors upregulated distinct signaling pathways that correlate with aggressive tumor phenotypes such as STAT3 pathway." (PMID 36330485, 2022). "Unresponsive TAb2 tumors upregulated distinct signaling pathways that correlate with aggressive tumor phenotypes." (PMID 35366939, 2022). "Our results showed that the number and percentage of CD11b+F4/80+ TAMs were markedly increased when BM cells were cultured with TAb2 tumor cells in a time-dependent manner." (PMID 35366939, 2022). "Our data showed that both culture supernatant and cell lysate of TCh3 tumor cells contained a higher level of CXCL17 and CXCL16 than those of TAb2 tumor cells, in line with our RNA-seq data." (PMID 35366939, 2022). "H&E staining data showed that TAb2 tumors were poorly differentiated, which was further validated by IF results showing TAb2 tumor undergoing EMT." (PMID 35366939, 2022). "Taken together, our results suggest that increased TAMs, and specifically M2 population, were attributed to TAb2 tumor-derived CSF1 and VEGF." (PMID 35366939, 2022). "TAb2 tumor cells drastically expanded F4/80+ TAMs from bone marrow precursors, requiring CSF1 and VEGF." (PMID 35366939, 2022). "We found that inhibiting CSF1R or VEGFR significantly reduced the number of CD11b+F4/80+ TAMs and particularly the number and percentage of M2 TAMs (F4/80+CD206+CD86−) generated from co-culture with TAb2 tumor cells." (PMID 35366939, 2022). "We found that co-culturing BM precursors with TAb2 tumor cells still led to a significant increase of CD11b+F4/80+ TAMs in the transwell system, whereas BM only or BM cells co-cultured with TCh3 tumor cells failed to do so." (PMID 35366939, 2022). "To test this, we examined the phosphorylation level of STAT3 (p-STAT3) using western blotting and found that TAb2 tumor indeed expressed a much higher level of p-STAT3." (PMID 35366939, 2022). "Furthermore, TAB2's influence extends beyond direct PD‐L1 regulation, potentially affecting the tumour immune microenvironment by impacting inflammatory cytokine production and immune cell infiltration." (PMID 40133221, 2025). "Second, our discovery that TAB2 works through the NF‐κB pathway suggests that existing NF‐κB inhibitors might be effective in treating resistant tumours, particularly when combined with standard chemotherapy." (PMID 40133221, 2025).
tumor (continued). "To test how tumor cells affect the proliferation and differentiation of myeloid cells, we employed a co-culture system established previously by our group using BM cells that contain myeloid precursors and are co-cultured with TAb2 tumor cells." (PMID 39596341, 2024). "The presence of TAb2 tumor cells promoted the expansion of TAMs (66.3%) in the group of BM+TAb2." (PMID 39596341, 2024). "We showed that TAb2 tumor cells expressed higher levels of CSF1, VEGF, HGF and CXCL12." (PMID 35366939, 2022). "IPA identified predicted pathways and networks for DEGs by TAb2 and TCh3 tumor cell lines." (PMID 35366939, 2022). "TCGA data revealed that TAB2 were distinctively upregulated in tumor tissues." (PMID 35978886, 2022). "In conclusion, our study demonstrated that TAB2 is closely correlated with OSCC tumor progression." (PMID 35978886, 2022). "TAB2 can promote proliferation and inhibit apoptosis by regulating tumor-related pathways." (PMID 35978886, 2022). "Furthermore, we found that co-culturing TAb2 tumor cells with BM cells resulted in drastic expansion of F4/80+ TAMs and CD206+ M2-TAMs, which is independent of cell-cell contact, suggesting a major role of secretory factors in promoting TAM differentiation." (PMID 35366939, 2022). "Furthermore, TAB2 expression differed by clinicopathological parameters: TAB2 upregulated with tumor grade 4 compared with lower tumor grade." (PMID 35978886, 2022). "Lastly, we found that TAb2 tumor expressed a higher level of p-STAT3." (PMID 35366939, 2022). "Further, miR‐7 mimics or the silencing of TAB2 could effectively abrogate the tumour progression induced by circ‐WHSC1 overexpression." (PMID 34551195, 2021). "VEGF pathway was predicted to be activated in TAb2 tumors, and VEGF has been shown to promote monocyte recruitment and tumor angiogenesis." (PMID 35366939, 2022). "For example, TAb2 tumors expressed a higher level of CSF1, VEGF-C and VEGF-D, and TAb2 tumor cells drastically expanded F4/80+ TAMs from bone marrow precursors in a CSF1 and VEGF dependent manner." (PMID 36330485, 2022). "All results indicated that tumours with a higher expression of circ‐WHSC1 had a relatively lower level of miR‐7 and higher mRNA and protein levels of TAB2." (PMID 34551195, 2021). "MAP3K7 requires TAK1-binding protein 1 (TAB1), TAB2, and TAB3 to trigger NF-κB activation, which is a key transcription factor for tumor initiation and malignancy." (PMID 31214512, 2019). "In the present study, down-regulation of TAB2 increased fibronection expression, which is involved in nickel-induced EMT and can subsequently promote tumor metastasis." (PMID 29127306, 2017). "The TAB2 polypeptide is additionally identified to facilitate the activity of EMT and the PI3K-AKT signaling axis, which are related to the growth and spread of tumor cells via indirectly activating NFκB." (PMID 39768951, 2024). "After binding with dsDNA, SOX2 is suggested to activate the kinase TAK1 and its binding partner TAB2 (Tab2/TAK1 complex) to trigger the NF-κB pathway, thus may lead to tumor growth and metastasis." (PMID 37122745, 2023). "As thus, TAB2 is critical to the regulation of EMT and PI3K-AKT signaling pathways and may serve as a therapy target of tumor metastasis." (PMID 35978886, 2022). "In addition, we found the function of TAB2 in promoting tumor progression in OSCC cell lines, and we creatively discovered the potential function of TAB2 in regulating EMT and PI3K-AKT pathways." (PMID 35978886, 2022). "We observed a variable percentage of different populations of myeloid cells (e.g., M-MDSC) upon co-culture with TAb2 or TCh3 tumor cells, albeit lacking a consistent pattern." (PMID 35366939, 2022). "In this study, a total of 12 genes, including TRAF, IRAK, TAB2, TLR, IL1R, and MYD88, harboured nonsilent mutations, indicating the activation of the NF-kB signalling pathway in tumour cells." (PMID 29127303, 2017).
tumor (continued). "The presence of TAb2 tumor cells did not expand PMN-MDSC; instead, it significantly reduced the percentage of PMN-MDSC, compared with the BM-only control, suggesting that a vast majority of BM cells remained as immature PMN-MDSC in the absence of other stimuli." (PMID 39596341, 2024).